INS (insulin)
Diseases named in the same sentence as INS in open-access papers (continued):
Sharing a sentence is not in itself a finding about the gene and the disease.
Obesity (continued). "Although macrophage insulin signaling is impaired in cardiometabolic disease (obesity and T2D, atherosclerosis, and heart failure), insulin-resistant macrophages have increased glucose uptake, glycolysis, and glucose oxidation." (PMID 39198360, 2025). "The VSL#3 strain probiotic, the only probiotic currently classified as a medical food, has demonstrated the capability to increase butyrate production and GLP-1 secretion, thereby protecting against diet-induced obesity and insulin hypersensitivity." (PMID 40564077, 2025). "miRNAs play a critical role in obesity by regulating the target genes involved in lipid metabolism, insulin signaling, and inflammation." (PMID 40699679, 2025). "Preclinical studies have shown that inhibiting GIP receptors improves insulin sensitivity and reduces obesity." (PMID 40192745, 2025). "Adiponectin, though decreased in obesity and promising in preclinical studies as insulin-sensitizing and anti-inflammatory, shows inconsistent links with human cognitive decline, variably associated with both protective and risk profiles across studies." (PMID 41155642, 2025). "Anti-obesity of probiotics is related to improvements in lipid metabolism, insulin sensitivity, anti-inflammation, or control of intestinal hormones like leptin or GLP-1, which is frequently accompanied by modulating the intestinal microbiota." (PMID 40218949, 2025). "The primary endpoint was insulin sensitivity, reflecting its central role in the pathophysiology of obesity and T2DM." (PMID 41025205, 2025). "Obesity is now often seen at the time of T1D diagnosis and can worsen during treatment as a result of intensive insulin regimens." (PMID 41199877, 2025). "Under insulin-resistant conditions, such as obesity, pancreatic β cells are well known to adaptively proliferate and secrete more insulin to prevent blood glucose elevations." (PMID 40337860, 2025). "Probiotics influence obesity by effectively regulating the gut’s microbial balance, reducing insulin resistance, and improving feelings of fullness." (PMID 41163054, 2025). "Subjects with obesity had elevated fasting plasma glucose, fasting plasma insulin, and HOMA-IR index compared with lean subjects." (PMID 40666326, 2025). "Despite our patients with overweight or obesity exhibiting significantly altered metabolic profiles at recruitment, biochemical analyses revealed significant reductions in fasting glucose, insulin, HbA1c, lipid profile parameters, and liver enzymes." (PMID 41010457, 2025). "This phenotypic shift supports insulin secretory capacity and contributes to metabolic homeostasis even under conditions of obesity and hyperglycemia." (PMID 41278909, 2025). "A recent study showed that the upregulation of spliced X-box binding protein 1 (Xbp1s) in AGRP neurons reverses diet-induced obesity and improves leptin and insulin resistance." (PMID 40531768, 2025). "Almost all studies report that PYY3–36 exhibits both anti-obesity and insulin-sensitizing properties, making it a promising candidate for T2D management." (PMID 41228539, 2025). "A decreased peripheral insulin sensitivity was reported after seven-day oral vancomycin use in males with obesity and metabolic syndrome compared to baseline, but this study did not include a control group." (PMID 41243448, 2025). "Obesity-associated inflammation promotes adipocyte lipolysis, leading to chronic FFA release and insulin resistance." (PMID 41157128, 2025). "In our study, we also conducted subgroup analyses based on BMI levels and found that obesity exhibited more dangerous tendencies across several key indicators including blood glucose, insulin, and TyG index." (PMID 40529828, 2025). "While studies on Acorus gramineus polysaccharides are limited, related compounds from Rhizoma Acori Tatarinowii have shown anti-obesity and lipid-lowering effects through gut microbiota modulation and improved insulin sensitivity." (PMID 40557240, 2025).
Obesity (continued). "In energy metabolism, NAD(P)H is consumed by NAD(P)H oxidase (NOX) to generate reactive oxygen species (ROS), which inhibit insulin secretion and disrupt glucose and lipid homeostasis, contributing to obesity." (PMID 40507161, 2025). "Chronic ER stress, often associated with obesity, leads to sustained IRE‐1α activation, which can impair insulin signaling pathways." (PMID 40145401, 2025). "This is likely due to the fact obesity has a positive effect on insulin levels and the insulin increases postprandial urinary calcium excretion." (PMID 40177183, 2025). "These processes lead to progressive β-cell failure and impaired insulin secretion, particularly in the context of obesity or prolonged hyperglycemia." (PMID 41473243, 2025). "In CKM stage 2, we should consider SGLT2i for CKD, and GLP-1RA for class 2 obesity or greater (BMI ≥ 35 kg/m2), HbA1c ≥ 9%, or high insulin requirements." (PMID 40868177, 2025). "In obesity, insulin’s effects are impaired, leading to IR, marked by mild hyperglycaemia and hyperinsulinaemia in fasting and postprandial states." (PMID 40136716, 2025). "Inhibition or modulation of PTP1B improves insulin sensitivity, glycemic control, and resistance to diet-induced obesity." (PMID 41011980, 2025). "We specifically assess its ability to enhance RSG’s insulin-sensitizing properties while counteracting its pro-obesity effects." (PMID 41471299, 2025). "Thermogenic adipose tissues (brown or beige fat), with their remarkable ability for increasing energy expenditure and insulin sensitivity, have emerged as promising targets for therapeutic interventions against obesity and related metabolic diseases." (PMID 40324882, 2025). "Our new observations define molecular events that help explain how increased extracellular matrix production in subcutaneous WAT can be tempered to maintain insulin sensitivity in obesity." (PMID 40471675, 2025). "These benefits are achieved by promoting fat hydrolysis and enhancing insulin action, countering diet-induced obesity." (PMID 40432896, 2025). "Deficiencies or excesses of certain vitamins and minerals can perturb adipokine secretion, insulin sensitivity, and mitochondrial function, thereby contributing to cardiometabolic diseases such as obesity, type 2 diabetes, and heart failure." (PMID 41470890, 2025). "The traditional obesity model, based on the balance between energy intake and expenditure, is gradually being supplemented by alternative concepts, notably the carbohydrate–insulin model." (PMID 41465237, 2025). "Adiponectin, known for its insulin-sensitizing and anti-inflammatory effects, exhibits decreased levels in obesity and metabolic syndrome." (PMID 41187309, 2025). "Microarray analysis revealed that hepatic mRNA affected the expression of genes involved in inflammation, lipid metabolism, lipid synthesis, and insulin signaling, leading to improvements in obesity." (PMID 39942605, 2025). "Obesity promotes cancer through a complex interplay of biological disruptions, including elevated insulin levels and insulin-like growth factors (IGF), chronic inflammation, and metabolic dysfunction." (PMID 41139777, 2025). "Lactobacillus reuteriJ1 has been found to treat obesity by regulating lipid and glucose metabolism, reducing fat mass, dyslipidemia, glucose homeostasis, and insulin sensitivity." (PMID 40295195, 2025). "The findings of this study show adverse changes in lipid and carbohydrate metabolism in children with obesity, including higher concentrations of triglycerides, glucose, insulin, and HOMA-IR and lower concentrations of HDL." (PMID 39931045, 2025). "We report novel bioenergetic differences in both PBMCs and platelets from insulin resistant children with overweight/obesity, namely elevated mitochondrial respiration in PBMCs and reduced mitochondrial respiration and glycolysis in platelets." (PMID 40525760, 2025).
Obesity (continued). "This systematic review aims to evaluate the effectiveness of various exercise interventions in improving cardiovascular risk factors—specifically lipid profiles, blood pressure, BP levels, and insulin sensitivity—in men with overweight or obesity." (PMID 40005372, 2025). "Target therapies for NF-κB signaling in obesity has been a long-standing goal, due to its chronic inflammatory activation that leads to insulin resistance and adipose tissue dysfunction." (PMID 41463063, 2025). "In particular, both FABP4 and FABP5 have emerged as key contributors to obesity-induced IR: their dual silencing in white adipose tissue significantly reduced inflammation and improved insulin sensitivity in preclinical models." (PMID 41372973, 2025). "Either genetic or pharmacological inhibition of PTGR2 prevented diet-induced obesity, improved insulin sensitivity, glucose tolerance, and ameliorated hepatic steatosis without fluid retention or osteoporosis." (PMID 40119175, 2025). "This study provides novel insights into the relationship between the TNF-α -308 G/A polymorphism, dietary antioxidants, and nutrient–gene interactions in the regulation of insulin levels among Spanish adults with obesity." (PMID 40732969, 2025). "Experimental data have consistently demonstrated that diet-induced obesity models, where mice are colonized with microbiota from obese donors, develop increased fat accumulation, impaired insulin sensitivity, and intestinal barrier dysfunction." (PMID 41010468, 2025). "In summary, the biological basis linking blood heavy metals, urinary sodium, and obesity involves disruptions in adipocyte function, oxidative stress, inflammation, endocrine signaling, fluid balance, appetite regulation, and insulin resistance." (PMID 39888952, 2025). "We further measured glucose and insulin levels to determine if prevention of obesity by CDDO-EA coincided with a reduction in hyperglycemia and hyperinsulinemia." (PMID 40564946, 2025). "This study demonstrates that obesity-induced hyperinsulinemia accelerates epiphyseal growth plate maturation through aromatase upregulation, highlighting the insulin-aromatase axis as a key regulator of skeletal growth." (PMID 41329658, 2025). "TGR5 represents a compelling molecular target for addressing the multifactorial pathogenesis of obesity, encompassing energy imbalance, insulin resistance, and dysregulated gut hormone signaling." (PMID 41153686, 2025). "All HH subjects had altered insulin sensitivity with a relatively large spectrum, whereas eugonadal men with obesity presented normal or only modestly elevated HOMA-IR." (PMID 39885510, 2025). "Individuals with obesity have reduced insulin-stimulated phosphorylation of IRS1 and Akt and lipid oxidative capacity and higher levels of intramuscular triacylglycerol." (PMID 40522819, 2025). "High levels of IFI16 in human adipose tissue are associated with larger adipocyte size and reduced insulin‐stimulated glucose uptake, suggesting a link between IFI16 expression and metabolic dysfunction in obesity." (PMID 39158380, 2025). "These shared features plausibly converge on vascular integrity, insulin sensitivity, gut–brain inflammatory signaling, and oxidative stress, which are central to the diet–obesity–brain axis reviewed here." (PMID 41228565, 2025). "The intricate connection between obesity and dyslipidemia is directly influenced by triglyceride levels, insulin resistance, and body fat distribution." (PMID 40108925, 2025). "Across cohorts, higher IMAT correlates with lower insulin sensitivity and poorer muscle quality in established obesity/T2DM, and human biopsy/co-culture studies show paracrine impairment of myofiber insulin action." (PMID 41002965, 2025). "Serum insulin levels were significantly elevated in HFD-fed rats (p < 0.01 vs. control), consistent with metabolic dysregulation associated with obesity." (PMID 40867531, 2025).
Obesity (continued). "In the context of obesity and IR, increased levels of insulin and aldosterone can activate endothelial sodium channels via mineralocorticoid receptors, resulting in excessive sodium influx and stiffening of the cortical actin cytoskeleton." (PMID 40841630, 2025). "Increased DAG in the steatotic liver was proposed to originate from increased fatty acid availability through increased lipolysis in insulin-resistant adipose tissue of subjects living with overweight and obesity." (PMID 41196673, 2025). "Regular physical activity enhances this flexibility, improving fat oxidation and insulin sensitivity in individuals with obesity." (PMID 41305652, 2025). "Obesity leads to unhealthy changes in adipose tissue, which is crucial for maintaining insulin sensitivity and preventing MASLD." (PMID 40431370, 2025). "Some evidence showed that enhanced insulin signaling in adipocytes can protect against ATM infiltration during obesity." (PMID 41141634, 2025). "As expected, obesity contributed significantly to higher values of BMI, insulin, glucose, HOMA-IR, blood pressure, triglycerides and FAI and lower levels of HDL-C and SHBG." (PMID 39958263, 2025). "The in vivo application of the anti-inflammatory and insulin-sensitizing effects associated with GPR120 stimulation, which are promising tools for the prevention and treatment of obesity, is very difficult." (PMID 40141148, 2025). "pPGSs for Beta Cell 1, Hyper Insulin are dramatically higher in eastern populations, while pPGS for Obesity is higher in western populations." (PMID 41001674, 2025). "The impact of insulin's effects on target tissues, referred to as insulin sensitivity, is affected by multiple physiological elements, where obesity is considered a primary determining factor." (PMID 40786169, 2025). "The high-frequency and high-centrality keywords such as “body composition” “body mass index” “skeletal muscle” “insulin resistance” “metabolic syndrome” and “skeletal muscle mass” signified that the field had evolved beyond simple obesity." (PMID 41164363, 2025). "In summary, in mice, exercise reduces obesity-associated inflammation and fibrosis in WAT, improves glucose and insulin homeostasis, and increases KYNA levels, which enhance fatty acid oxidation, reduce fat storage, and improve glucose tolerance." (PMID 40522819, 2025). "Obesity is the core metabolic driving factor of multiple comorbidities, mainly exerting its effects through two pathways: inflammation and insulin resistance." (PMID 41458407, 2025). "In another clinical trial that assessed a cohort with prediabetes and overweight/obesity, fasting plasma LEAP2 levels were inversely associated with insulin sensitivity and positively associated with BMI, body weight, and fat mass." (PMID 40214973, 2025). "The findings highlight the critical role of ER stress in metabolic syndromes, including obesity, by demonstrating its effects on reducing lipid accumulation and inflammation, enhancing insulin sensitivity, and improving cardiovascular function." (PMID 41018420, 2025). "Weight gain and obesity result in β‐cell stress by increasing the need of endogenous insulin to compensate for increasing plasma glucose concentrations." (PMID 40888596, 2025). "NLRP3 inflammasome is capable of sensing obesity-related danger signals and is closely related to insulin signals, glucose tolerance, and IR." (PMID 41264598, 2025). "Because mutant females were protected from diet-induced obesity, we reanalyzed the insulin and glucose tolerance tests, at this time correcting the results for body mass, nevertheless, the results persisted." (PMID 41219904, 2025). "Dietary EAA supplementation has been shown to activate BAT thermogenesis and promote UCP1-dependent mitochondrial uncoupling, thereby conferring protection against obesity and improving insulin sensitivity." (PMID 40983641, 2025).
Obesity (continued). "Several relevant transcription factors (TFs) bind to the promoter region of ZPR1, including PPARG (functioning in insulin sensitivity and obesity) and HNF4A (triggering genes involved in glucose, fatty acid, and cholesterol metabolism)." (PMID 40665476, 2025). "In obesity, an increase in free fatty acids and pro-inflammatory cytokines provokes chronic, low-grade inflammation, which diminishes insulin sensitivity in skeletal muscle, hepatic tissue, and adipose tissue." (PMID 41439931, 2025). "Adipokines such as leptin and insulin play an important role in the regulation of appetite and energy metabolism, and their resistance usually leads to the development of obesity." (PMID 41199858, 2025). "The metabolic alterations observed reflect progressive pathophysiological transitions from diet-induced obesity to insulin-resistant, diabetic states." (PMID 41002949, 2025). "For example, beneficial bacteria such as Bifidobacterium and Lactobacillus, which are in high abundance in animal intestinal tract, can prevent obesity by enhancing the intestinal barrier, improving insulin sensitivity and improving metabolic disorders." (PMID 40384781, 2025). "Among them, the metabolic pathway, insulin signaling pathway, and lipid and atherosclerosis pathways have been recognized as crucial regulators in obesity development." (PMID 40438591, 2025). "In epididymal white fat tissue, the overexpression of Blnc1 partially mitigated glucose metabolism and dyslipidemia, improved insulin sensitivity, and protected against diet-induced obesity hepatic steatosis." (PMID 41226441, 2025). "The progression of obesity often leads to elevated secretion of Rbp4 by adipocytes, impairing insulin sensitivity and accelerating lipolysis in adipose tissue." (PMID 38474824, 2024). "This study shows that whole-body insulin sensitivity and tissue-specific intestinal insulin sensitivity are impaired in obesity." (PMID 39458548, 2024). "Together, these data indicate that myeloid cell-derived miR-6236 influences adipose tissue insulin signaling and global metabolic homeostasis during obesity." (PMID 38918428, 2024). "Exercise robustly reversed the activation of this pathway and enhanced insulin signaling, presenting a novel mechanism by which exercise improves insulin action in obesity and T2D." (PMID 39599740, 2024). "The present study concludes that the addition of 40 mM succinic acid to drinking water effectively inhibits high-fat diet-induced obesity in mice, enhances glucose and lipid metabolism, improves insulin sensitivity, and induces adipose tissue browning." (PMID 39599615, 2024). "Some beneficial results of TRE have been described at the metabolic level in people with obesity or overweight, including an increase in lipid oxidation, a decrease in plasma glucose levels, and an improvement of insulin sensitivity." (PMID 37993559, 2024). "It has been found that excessive selenium intake can disrupt the insulin signaling pathway, leading to hyperglycemia and obesity, contributing to systemic inflammation, which is a significant factor in OA and hypertension." (PMID 38292866, 2024). "FSTL1 plays a significant role in inflammation, glucose metabolism, and insulin sensitivity, particularly in the context of obesity and exercise." (PMID 38786764, 2024). "ADSCs-Exo has been demonstrated to enhance insulin sensitivity, mitigate obesity, and alleviate hepatic steatosis in a murine model of obesity." (PMID 39684778, 2024). "The characterization of obesity in numerous studies varied significantly, assessed through body weight, body composition, glucose tolerance, and insulin tolerance." (PMID 38388878, 2024). "Many genes on this list are involved in different processes associated with T2DM development, such as obesity (SREBF1 and H6PD), inflammation (TGFB1), and insulin resistance (RPTOR and AKT1)." (PMID 39273245, 2024).